ZNF705EP (zinc finger protein 705E, pseudogene)
Description:
May be involved in transcriptional regulation.
Synonyms: formerly ZNF705E
Gene: Transcribed unprocessed pseudogene on chromosome 11 (71,816,512 to 71,821,548, reverse strand). Ensembl gene ENSG00000214534.
Subcellular location: Nucleus
Pathways (Reactome):
Gene expression (Transcription): Generic Transcription Pathway
Genetic constraint (gnomAD): Loss-of-function variants: 11 observed, 15.32 expected, observed/expected ratio (o/e) 0.72, 90% interval 0.45 to 1.19. The upper end of that interval is the gene's LOEUF score, 1.19, which puts it in group 5 of 6, group 1 being the genes least tolerant of losing a copy. Missense variants: 311 observed, 338.9 expected, observed/expected ratio (o/e) 0.92, 90% interval 0.84 to 1.01. Synonymous variants: 110 observed, 112.35 expected, observed/expected ratio (o/e) 0.98, 90% interval 0.84 to 1.15.